INS (insulin)
Diseases named in the same sentence as INS in open-access papers (continued):
Sharing a sentence is not in itself a finding about the gene and the disease.
metabolic disorders (continued). "Individuals with metabolic disorders or inflammatory conditions may have altered lipid metabolism, insulin sensitivity, or inflammatory pathways that can influence both efficacy and mechanisms of nutritional interventions." (PMID 40871660, 2025). "The pathogenesis of includes mainly multiple factors (such as intestinal flora disorders, inflammation, oxidative stress, ER stress, and metabolic disorders) induced by impaired islet function, insufficient insulin secretion, or a decreased ability to perceive glucose." (PMID 40290429, 2025). "The modulation of postprandial insulin response, as seen in this study, could have implications for improved glucose utilization an important element of metabolic disorders." (PMID 40490608, 2025). "Additionally, abnormal OGTT results can indicate glucose metabolic disorders, reflecting insulin secretion impairment or β-cell dysfunction." (PMID 40375950, 2025). "Insulin resistance (IR) represents a fundamental endocrine dysfunction wherein target tissues demonstrate impaired sensitivity to physiological insulin action at both receptor and post-receptor levels, constituting a core metabolic disorder in numerous chronic diseases." (PMID 41450551, 2025). "By addressing current limitations and pursuing targeted research strategies, a clearer understanding of the insulin–bone axis can be achieved, ultimately driving the development of personalised interventions to preserve bone health in individuals with metabolic disorders." (PMID 40564223, 2025). "GDF-15 activates GFRAL, influencing metabolism and insulin sensitivity, and may be involved in the development of metabolic disorders, oxidative stress, and inflammation." (PMID 41019919, 2025). "Depletion of CRIg+ cells results in the spread of mEVs into distant metabolic tissues, subsequently exacerbating tissue inflammation and metabolic disorders; treatment of obese mEVs directly triggers inflammation and insulin resistance of hepatocytes and adipocytes." (PMID 40129979, 2025). "Carbohydrate metabolism disorders were observed in five patients: one prediabetic patient, one diabetic patient treated with oral antidiabetic drugs, and three diabetic patients requiring intensive insulin therapy with high daily doses of insulin > 40 units." (PMID 40427109, 2025). "Protects against metabolic disorders by enhancing insulin sensitivity and reducing inflammation." (PMID 40013194, 2025). "Studies have shown that specific essential oil components can improve metabolic disorders, enhance insulin sensitivity, and lower blood glucose, and blood lipids through a variety of mechanisms, thus playing an active role in the management of metabolic diseases." (PMID 41199858, 2025). "Through an analysis of adipokine functions, this review examines their impact on metabolic dysregulation by evaluating their involvement in inflammatory processes as well as insulin signaling and hormonal system interactions to understand their multifaceted role in metabolic diseases." (PMID 40013194, 2025). "Moreover, research in recent years has revealed several important connections between insulin and cognitive processes, particularly in the context of aging, metabolic disorders, and neurodegenerative diseases." (PMID 40725728, 2025). "Regular PA controls weight, improves insulin sensitivity, and prevents metabolic disorders." (PMID 40735200, 2025). "Strength training, known to enhance insulin sensitivity and promote the secretion of health-protective myokines like exerkines, should be prioritized in public health initiatives to mitigate the growing burden of metabolic diseases." (PMID 40137324, 2025). "The discovery that the Trib3 isoform in mice inhibits insulin responses by binding Akt kinase to prevent its phosphorylation-activation by the insulin receptor (Insr) led to extensive studies on the role of Trib proteins in insulin responses and metabolic disease." (PMID 40292740, 2025).
metabolic disorders (continued). "On the other hand, SCFAs (e.g., propionate) promoted by DI-GM enhance insulin sensitivity by activating the AMPK pathway, while the low-inflammatory environment of DII reduces the interference of inflammatory factors on insulin signaling, jointly improving metabolic disorders." (PMID 40746546, 2025). "However, since the 2000s, 28 new non-insulin peptide drugs have been approved worldwide, and more than 80 new peptide drugs from other research areas, mainly metabolic disease, and oncology, and more than 170 peptides, are in active clinical development." (PMID 39974747, 2025). "Third, designing combination therapeutic regimens that pair peripheral interventions, like insulin sensitizers for metabolic disorders, with central anti-inflammatory agents, a strategy aimed at breaking the self-perpetuating “brain–periphery” vicious cycles underlying many chronic diseases." (PMID 41294833, 2025). "By altering hormonal balance, endocrine disruptors may impact insulin sensitivity and glucose regulation, contributing to the development of metabolic disorders." (PMID 41450548, 2025). "Clinical studies have shown a practical correlation between fluctuations in endogenous LF levels and metabolic disorders, and LF may regulate glucose metabolism, insulin homeostasis and lipid metabolism." (PMID 40313489, 2025). "This approach recognises that insulin-induced mitochondrial, metabolic and endocrine dysregulation can occur below standard thresholds and provides a more sensitive and specific means of identifying early metabolic disease." (PMID 41586225, 2025). "Intracellular lipid accumulation in muscle cells may exacerbate metabolic disorders, higher intramuscular lipid content is observed in insulin-resistant subjects." (PMID 38957396, 2024). ",34 described this type of inflammation as metabolic inflammation, and they found that obese mice released more Tumor Necrosis Factor (TNF) in adipose tissue, resulting in poor insulin sensitivity and glucose homeostasis, thus linking inflammation with metabolic disorders." (PMID 38875754, 2024). "Regarding the PO group, a significant decrease in the HOMA index was recorded, from an initial average of 4.36 to a final average of 0.94, highlighting the effectiveness of the interventions applied in improving insulin sensitivity and managing metabolic disorders within this study." (PMID 38732523, 2024). "The identified chemical switch linking FA metabolism to GSIS may help better understand the mechanisms by which β cells integrate different nutrients to regulate insulin secretion and shed new insights into the pathogenesis of metabolic diseases." (PMID 39442620, 2024). "T2DM is a complex metabolic disorder characterized by reduced insulin production and resistance." (PMID 39479098, 2024). "A survey of the literature presented in the review provides evidence for the belief that very individualized treatment, including interactions of angiotensins and vasopressin with insulin, should be applied in patients suffering from both the cardiovascular and metabolic diseases." (PMID 38279313, 2024). "Therefore, improving insulin-mediated glucose metabolism by targeting the IRS/PI3K signaling pathway is an effective strategy for alleviating metabolic diseases, including T2DM." (PMID 39337550, 2024). "The increase in Anaerostipes in the YMETA group suggests that the DF supplement may enhance butyrate production, thereby improving insulin sensitivity and reducing metabolic disorder risks." (PMID 39064648, 2024). "In terms of metabolism and metabolic disease, the role of HIF1α has been well-established in the regulation of sterile inflammation, tissue fibrosis, insulin action, and lipid handling in various peripheral metabolic organs/tissues including liver, intestine, pancreatic β-cell, and adipose tissue." (PMID 38509584, 2024).
metabolic disorders (continued). "It is a metabolic disorder characterized by high blood sugar levels, resulting from a malfunction in carbohydrate metabolism, insufficient secretion of insulin by the pancreas, or the body’s resistance to insulin, leading to elevated blood and urine sugar levels." (PMID 39178273, 2024). "The literature has not fully explored the specific mechanisms of how fatty acids affect insulin signalling through the NLRP3 inflammasome, and how this effect may be linked to the development of metabolic disease." (PMID 39717099, 2024). "Another consequence of metabolic disorders is the disruption of the endocrine system, which leads to hormonal changes, such as elevated insulin and leptin levels, insulin resistance in peripheral tissues, and decreased adiponectin, all of which contribute to reduced fatty acid oxidation." (PMID 39839806, 2024). "This inflammatory response disrupts insulin and leptin signaling and affects neuronal function through the accumulation and activation of astrocytes—both important contributors to the onset and progression of various metabolic diseases." (PMID 39590331, 2024). "The prevailing theory suggests that metabolic disorders could promote thyroid cell growth through interactions between insulin and thyroid stimulating hormone." (PMID 38774231, 2024). "Insulin and leptin were reliable biomarker of glycolipid metabolism disorders." (PMID 38962449, 2024). "Excessive insulin and androgen may impair the quality of oocytes and induce metabolic disorders in theca cells and granulosa cells." (PMID 38978625, 2024). "Notably, insulin stands as the sole hormone capable of decreasing blood glucose levels, making the assessment of insulin content a crucial aspect in understanding metabolic diseases related to insulin." (PMID 39188698, 2024). "A series of studies on the role of HAP1 in insulin release may provide a new therapeutic target for metabolic disorders that are predominantly characterized by defective insulin release." (PMID 38975245, 2024). "Thus, further basic science is necessary to provide new insights into molecular mechanisms involved in the improvement of insulin sensitivity in the liver, thus increasing understanding of these metabolic diseases’ pathogenesis." (PMID 38892230, 2024). "Insulin signal transduction is defective in metabolic diseases." (PMID 38957396, 2024). "Therefore, improving insulin sensitivity can be considered as an effective strategy for the prevention and treatment of these complex metabolic diseases." (PMID 39749015, 2024). "Hence, EGCG holds promising potential for ameliorating metabolic disorders by addressing lipid metabolism imbalance and insulin resistance through modulation of the UPS system." (PMID 39188976, 2024). "In conclusion, a positive feedback mechanism between ChREBP and progesterone may be an important factor for regulating insulin sensitivity and lipid accumulation during pregnancy under metabolic disorders." (PMID 38532128, 2024). "The evidence suggests that exosomal long non-coding (exo-lncRNAs) are altered in the biofluids (such as blood, vitreous humor, and tears) of patients with metabolic disorders and correlate with key metabolic parameters, including body mass index, inflammation, and insulin sensitivity." (PMID 39765643, 2024). "Due to the role of gut microbiota in the regulation of glucose and insulin homeostasis, probiotics with beneficial properties have emerged as an alternative therapeutic tool to ameliorate metabolic diseases-related disturbances, including fat excess or inflammation." (PMID 38279322, 2024). "This hypothesis is consistent with clinical data indicating that primary diagnostic markers like insulin, blood pressure, triglycerides, and HDL, underpin the importance of using metformin and statins to manage complications of metabolic disease." (PMID 39070960, 2024). "This metabolic disorder is based on impaired B-cell secretion and tissue resistance to insulin." (PMID 37189777, 2023).
metabolic disorders (continued). "T2DM is a metabolic disorder in which insulin signaling is impaired from reaching its effectors." (PMID 37174622, 2023). "It remains to be determined whether caffeine influences insulin resistance or metabolic diseases by modulating Erysipelatoclostridium." (PMID 37049587, 2023). "Therefore, insulin should still be used to control blood sugar stability and to improve metabolic disorders in diabetic patients postoperatively." (PMID 37190523, 2023). "Most of the analyzed anthropometric and atherogenic indices may be useful tools in evaluating metabolic disorders, and, in particular, glucose and insulin abnormalities in PCOS women." (PMID 36837921, 2023). "Although the intricate mechanisms linking oxidative stress and metabolic disorders are yet to be fully understood, it is plausible to speculate that oxidative stress-induced complications impact the insulin signaling pathway." (PMID 37960168, 2023). "The PTP1B and TC-PTP phosphatases, being negative regulators of insulin and leptin signaling, are involved in the development of insulin and leptin resistance and mediate an increase in appetite, and the accumulation of excess adipose tissue in metabolic disorders." (PMID 36901928, 2023). "In this study, we found a significant negative correlation between peripheral glucose, lipid, HOMA-IR, IRS-1, and p-AKT levels, indicating that peripheral metabolic disorders may influence the sensitivity of the central insulin pathway." (PMID 38283741, 2023). "While these findings suggest that GM3 may function as an inhibitor of insulin signaling, it is controversial whether insulin signaling diminished by GM3 actually aggravates the pathological conditions in metabolic disorders." (PMID 36827398, 2023). "Indeed, AD is considered a metabolic disorder related to decreased brain glucose metabolism, involving brain insulin resistance and age-dependent mitochondrial dysfunction." (PMID 37626828, 2023). "The modulation of insulin signaling by lipid metabolites such as PA, DAG, and ceramide demonstrates the intricate balance between lipid homeostasis and glucose metabolism, revealing potential metabolic points of intervention for improving insulin sensitivity and combating metabolic disorders." (PMID 38203517, 2023). "We found that the BCD could deliver an accurate amount of a drug, such as exenatide, insulin, or glucagon, which was as effective as conventional injections in an animal model of metabolic disease." (PMID 36684080, 2023). "Furthermore, HFD led to metabolic disorders, including compromised glucose tolerance and insulin sensitivity, and increased blood glucose levels under fasting condition." (PMID 36894534, 2023). "It is a heterogeneous metabolic disorder caused by a lack of insulin production in the body or insulin resistance that can impair heart function." (PMID 38113243, 2023). "When it comes to glucose homeostasis, it appears that CBD maintains it, sensitises adipose tissue to insulin, and reduces fasting glucose levels, so it seems to be a potential target in this kind of metabolic disorder, but some research results are inconclusive." (PMID 37510734, 2023). "Furthermore, an inverse correlation was observed between the concentrations of iso-BCFAs and serum concentrations of CRP (inflammation marker), insulin and TG (connected with metabolic disorders)." (PMID 37850622, 2023). "Importantly, pharmacological inhibition of GSK3α improves insulin sensitivity and glucose tolerance in diet-induced diabetic mice, highlighting GSK3α as a therapeutic target for metabolic disorders." (PMID 36445308, 2023). "In specific cases, medications targeting metabolic disorders, such as insulin sensitizers, lipid-lowering agents or glucose-lowering medications, may be necessary." (PMID 38137918, 2023).
metabolic disorders (continued). "Myo-inositol (MI)—a 6-C sugar alcohol—with insulin-mimetic, anti-diabetic, lipid-lowering, and anti-inflammatory properties has exerted favorable effects on insulin resistance-related disorders and metabolic disease, while recent animal studies revealed its positive effects on liver function." (PMID 36824177, 2023). "Berberine shows significant effect on improving insulin sensitivity and metabolic disorders." (PMID 37483428, 2023). "Ongoing research will continue to shed light on the complex interplay between glucose metabolism, insulin sensitivity, and the gut microbiome, which may ultimately lead to more effective and personalized treatments for metabolic diseases." (PMID 37998523, 2023). "Continuously exposure to organic insecticide could contribute to insulin resistance and metabolic disorders in mammal and insects." (PMID 36860521, 2023). "Dysregulated insulin and estrogen signaling lead to metabolic diseases." (PMID 36942499, 2023). "It has been suggested that nesfatin-1 can improve insulin sensitivity and glucose uptake in muscle and AT while reducing hepatic glucose production and lipid accumulation, which can help prevent the development of IR and metabolic disorders, such as T2D." (PMID 38136166, 2023). "Among the validated genes, GNAS encoding the heterotrimeric Gs protein alpha-subunit (Gsα) that increases intracellular cAMP and activates PKA, promoting Ca2+ influx and insulin secretion by pancreatic β-cells, has been shown to be involved in both cardiac and metabolic disorders in humans." (PMID 37628941, 2023). "Recent studies indicate that palmitoleic acid increases insulin sensitivity, improves blood lipid profile, alters macrophage differentiation in rodent models and in cell culture, and has a potential impact on certain metabolic diseases." (PMID 36297306, 2022). "Irisin was previously found to improve myocardial functions in the diabetic heart in association with an improvement in insulin sensitivity and the PRAK pathway, revealing that irisin-enhanced insulin sensitivity modulates cardiac performance in metabolic disorders." (PMID 36297305, 2022). "Our study showed that DTE may ameliorate metabolic disorders in db/db diabetic mice by significantly lowering blood glucose, serum insulin level, TC, TG, LDL, and lightly improve the islet damage." (PMID 36176635, 2022). "A previous study showed that the isobutyric acid enhances glucose absorption and may lead to increased insulin sensitivity in persons with metabolic diseases." (PMID 35684581, 2022). "Reciprocally, changes in O-GlcNAc levels of specific proteins and sites are responsible for hepatic insulin resistance, glucose toxicity, insulin-induced de novo lipogenesis, necroptosis, and tissue fibrosis, contributing to the development of metabolic diseases." (PMID 35285892, 2022). "EVs transfected with an miR-133b mimic by the Exo-Fect and M2 polarized bone marrow-derived macrophages derived EVs packaged with miR-690 both enhanced glucose tolerance, insulin sensitivity, and thus provided a new insulin-sensitizing agent for the treatment of metabolic diseases." (PMID 35915850, 2022). "Thus, PPARγ agonists can be used as drugs against metabolic disorders, including T2D, by improving insulin sensitivity and reducing plasma glucose concentration." (PMID 36339572, 2022). "Cellular mechanisms that enhance whole-body insulin sensitivity may therefore help prevent the development of metabolic diseases." (PMID 36172277, 2022). "Further, sirtuins (SIRT) are known to exert various effects on insulin secretion, insulin sensitivity, gluconeogenesis, and glycolysis and could be a therapeutic target for a variety of metabolic diseases." (PMID 35458241, 2022). "In addition to its anti-tumorigenic effects, GE has anti-inflammatory and antioxidant properties against metabolic disorders by mediating insulin sensitivity, fatty acid metabolism, and reactive oxygen species (ROS)." (PMID 36558427, 2022).